IL6 (interleukin 6)
Diseases named in the same sentence as IL6 in open-access papers (continued):
Sharing a sentence is not in itself a finding about the gene and the disease.
Stroke (continued). "The molecular biomarkers that stand out as potential candidates for monitoring stroke prognosis include CRP, fibrinogen, IL-6 for the measurement of inflammation, NfL for neuroaxonal damage, and SOD activity for oxidative stress." (PMID 36699006, 2022). "Real-time quantitative PCR measurements suggested the prominent elevation of multiple pro-inflammatory cytokines and chemokines, including IL-1β, IL-6, TNF-α, CCL2, CXCL1, and CXCL10 after stroke." (PMID 35761277, 2022). "Serum concentration of IL-6 and TNF-α of the subgroups of stroke patients with a favourable and an unfavourable outcome after IV thrombolysis at admission, discharge, after 3 months, and after 1 year." (PMID 36142524, 2022). "The pro-inflammatory and acute-phase proteins IL-6 and CRP are important players in the inflammatory cascade and have been shown to be elevated after a stroke." (PMID 36430226, 2022). "Multiple biomarkers were associated with inflammation and showed the ability to predict outcomes or SAP events in stroke, such as CRP and IL‐6." (PMID 35849734, 2022). "There was also a statistically significant decrease in the release of IL-6, IL-1β, and TNF-α from trans-well co-cultures of MSCs with stroke derived monocytes as compared to co-cultures using healthy monocytes (p < 0.05)." (PMID 36277912, 2022). "The exacerbated stroke outcomes in diabetic mice were accompanied by the upregulated expression of inflammatory factors (including IL-1β, TNF-α, IL-6, CCR2, and MCP-1) in the ischemic brain." (PMID 35784349, 2022). "The better result of the combination of IL-6 and the clinical variables may show the additional benefit of IL-6 by capturing patients with an increased severity, such as the association with stroke size, which is not always reflected by the clinical scores e.g., NIHSS." (PMID 36430226, 2022). "In trans-well co-cultures of MSCs and monocytes isolated from stroke patients, we found statistically significant increased levels of IL-4 and MCP-1, and decreased levels of IL-6, IL-1β, and TNF-α." (PMID 36277912, 2022). "Further, they found that the level of serum exosomal miR-134 was positively correlated with the expression of IL-6 and hs-CRP, which were both reported to reflect the degree of brain ischemic damage and stroke." (PMID 36438184, 2022). "A positive relationship between stroke severity (NIHSS), physical disability (mRS), and IL-6 serum levels after 5 days, 3 months, and 1 year was reported." (PMID 36699006, 2022). "Macrophages/microglia are major source of inflammatory mediators (e.g., TGF-β, IL-6, IL-1β, or TNF-α) in stroke to activate the astrocyte TLR/NF-κB inflammatory pathway and further amplify neuroinflammation to exacerbate neuronal damage and stroke symptoms." (PMID 36159395, 2022). "In the gastrocnemius muscles of rats with stroke, R-7050 improved activated TNFRI/NF-κB, oxidative stress, and IL-6 pathways, as well as impaired insulin signaling." (PMID 34073455, 2021). "IL1B, IL10, TNF, IL6, and ICAM1 are closely related to the inflammatory response after stroke, among which IL-10 is an important anti-inflammatory factor, while L1B, TNF, and IL6 are proinflammatory factors." (PMID 33727944, 2021). "We have demonstrated that assessment of TNF-α, IL-6, and IL-10 levels in both NWS and SWS significantly differentiates stroke patients from healthy controls." (PMID 34433866, 2021). "TNF-α/IL-10 and IL-6/IL-10 ratio were also significantly higher in NWS and SWS of stroke patients, indicating an intensification of the inflammatory process and a limited anti-inflammatory role of IL-10." (PMID 34433866, 2021). "In accordance with the hypothesis that IL-6 trans-signaling is detrimental, while the classic one may exert protective effects, specific inhibition of trans-signaling mediators (i.e., using the chimeric protein sgp130Fc) may represent an interesting strategy for stroke therapy." (PMID 33770265, 2021).
Stroke (continued). "The core targets of PPI are TNF,IL-6,ALB,AKT1,VEGFA, and CREB1, which play a key role in the regulation of stroke by DZSM." (PMID 34754318, 2021). "All in all, Il-6 TNF-R1 and endostatin seem to be interesting candidates for further exploration as long-term mortality biomarkers after stroke." (PMID 33578805, 2021). "the primary result was the reduction of hs-CRP and IL-6 levels in a dose-dependent manner, associated with a reduced incidence of the composite outcome consisting in non-fatal myocardial infarction, non-fatal stroke, or cardiovascular death for the 150 mg and 300 mg dosages." (PMID 33770265, 2021). "The induction of IL-6 and chemokine CXCL-1 are dominant in the peripheral inflammatory response to stroke and can increase brain tissue injury as well as lead to BBB breakdown." (PMID 34393969, 2021). "Proinflammation cytokines, such as IL-6, IL-10, and TNF-α, have been shown to be elevated in the rat models of stroke that were subjected to a pretreatment of RIC." (PMID 34439830, 2021). "A cohort study of patients with acute ischemic stroke also found that the serum IL-6 levels in patients with poststroke epilepsy were significantly higher than those in patients without seizures, which could be regarded as an independent predictor of seizures in stroke patients." (PMID 33959658, 2021). "Cytokines are important immune mediators in the post-stroke response, so they have been studied as predictors of SAI, including pro-inflammatory IL-6 and anti-inflammatory IL-10." (PMID 34092245, 2021). "Counts of WBC and neutrophil, level of IL‐6, and CRP were significantly higher in CE or LAA, supporting the role of chronic inflammatory mechanism in stroke." (PMID 33314753, 2021). "In our patients, the content of pro-inflammatory TNF-α and IL-6 was higher, and anti-inflammatory IL-10 was lower in both NWS and SWS of stroke patients." (PMID 34433866, 2021). "Nevertheless, both the concentration (pg/mL), salivary output (pg/min), and specific content (per mg protein) of TNF-α and IL-6 were significantly higher, whereas IL-10 was statistically lower in NWS and SWS of stroke patients compared to controls." (PMID 34433866, 2021). "This was corroborated by literature publishing that TNF-α, IL-1B, IL-6 and IL-18 also independently predicted the occurrence of PSD in the acute to subacute period, and elevated IL-6, IL-10 and TNF-α correlates with PSD at one to three months post stroke." (PMID 33919670, 2021). "Atorvastatin alone reduced the release of IL-6, IL-8 and MCP-1 from co-cultures of stroke monocytes and MSCs." (PMID 33959001, 2021). "For example, in mouse ischemic stroke models, lymphocytes infiltrating into the whole stroke brain were complicated with inflammatory cytokines IL-1α, IL-1β, IFN-γ, TNF-α, and IL-6 at 2 weeks after stroke." (PMID 34421544, 2021). "In summary, in Wistar rats, IL-1β, IL-6, TGF-β, BDNF/TrkB and VEGF levels were increased at 24-h after stroke, IL-10 was increased at 30 days." (PMID 34408211, 2021). "In the middle cerebral artery-occlusion model, the expression of NOD2 is significantly elevated, and ablation of the NOD2 gene reduces stroke size and inflammation as indicated by lowered expression of NF-κB, MAPK, IL-6, and TNF-α." (PMID 34829993, 2021). "LCN2 monoclonal antibody (mAb) specifically targeted LCN2 in vitro and in vivo, attenuating the induction of LCN2 and pro-inflammatory mediators (iNOS, IL-6, CCL2, and CCL9) after stroke." (PMID 32872405, 2020). "We observed significantly higher levels of proinflammatory cytokines IL-1β, IL-6, and TNF-α in plasma of stroke mice and the BR therapy decreased the levels of these cytokines in plasma." (PMID 32843630, 2020). "Plasma NF-L levels were higher in stroke patients than in TIA patients and healthy controls, but IL-6 levels were similar." (PMID 32595585, 2020).
Stroke (continued). "A heightened peripheral inflammatory response—specifically, peak plasma IL-6, and CRP concentrations—is correlated with increased infarct volume at 7 days post-stroke, as well as worse functional outcome at 3 months." (PMID 32477259, 2020). "One month after LPS treatment, the priming of LPS induced significantly higher IL-1β, IL-6, and TNF-α production 24 h after the subsequent stroke, and infarct size was also exacerbated by the LPS priming." (PMID 33013828, 2020). "Our data showed that RIPC reduced the levels of pro-inflammatory cytokines IL-1β, IL-6 and IFN-γ in the blood, and IL-1β and IFN-γ in the brain in aged rats 48 h post-stroke, while the changes that were neutralized by the HIF inhibitor." (PMID 32210788, 2020). "RIPC reduced the levels of IL-1β, IL-6 and IFN-γ in the peripheral blood and the levels of IL-1β and IFN-γ in the ischemic brain 48 h post-stroke." (PMID 32210788, 2020). "Npas4 knock-out mice also exhibited higher levels of the pro-inflammatory cytokines IL-6 and TNF-α post-stroke, and stroke-induced upregulation of Npas4 was found in brain regions linked to emotion and cognition." (PMID 33335473, 2020). "The data demonstrated that BR therapy significantly reduced the levels of proinflammatory cytokines interleukin (IL)-1β, IL-6, TNF-α, and the chemokine, CXCL1, at 8 h post stroke and further reduced IL-6, IFN-γ, and TNF-α at 23 h post stroke." (PMID 32843630, 2020). "In the gut, IL-6 and TNF-α gene expression levels were significantly higher at 6-h and 24-h post-stroke in Ag mice compared to age-matched controls." (PMID 32429999, 2020). "In this study, an array of inflammatory cytokines including IL-1β, TNF-α, IL-6, cyclooxygenase (COX)-2, monocyte chemoattractant protein (MCP)-1, and chemokine (C-X-C motif) ligand 1 (CXCL1) at 6, 24, 48, and 72 h after stroke were analyzed by qRT-PCR." (PMID 32867781, 2020). "The largest study tested 14 different biomarkers, including interleukin 6 and CRP, and limited utility in stroke prediction was found." (PMID 32101136, 2020). "Several studies have shown that immune responses including IL6, IgA, CXCL16, TNFSF4, and IL10 were involved in stroke." (PMID 31899762, 2020). "Taken together, these studies show that genetic or pharmacological inhibition of these pro-inflammatory mediators (iNOS, IL-6, CCL2, CCL9) provides neuroprotection against stroke." (PMID 32872405, 2020). "In stroke, the inflammatory factors secreted by activated microglia (M1), such as TNF-α, IL-1β, and IL-6, are significantly elevated." (PMID 32733433, 2020). "Expression of IL-1α and IL-6 significantly increased after DCAL and was also the most upregulated in the stroke models." (PMID 33097782, 2020). "Pro-inflammatory cytokines, such as tumor necrosis factor alpha (TNF-α), interleukin 6 (IL-6), interleukin 1 beta (IL-1β), and monocyte chemoattractant protein-1 (MCP-1), were significantly increased in the CLEC14A-KO mice after stroke." (PMID 32019570, 2020). "IL-6 and TNF-α are pro-inflammatory factors, the elevated concentrations of which are observed, inter alia, during stroke." (PMID 33187206, 2020). "To verify the anti-inflammatory function of Gen after reproductively senescent stroke, we evaluated inflammatory factors, including TNF-α, IL-1β, IL-18, and IL-6 in ischemic penumbra area 24 h after reperfusion." (PMID 32625078, 2020). "Of note, SDMA and MCP-1 were correlated already at the early stage only hours after the acute event, while there were further correlations days after stroke between SDMA, MCP-1 and IL-6." (PMID 32150996, 2020). "We found that TMF-treated WT and AHRcKO mice showed significantly attenuated IL-1β, IL-6, and IFN-γ production in the brain after stroke." (PMID 31606043, 2019). "Many biomarkers offer the potential to predict the outcome of stroke, including TG/HDL-C, IL-6, NT-proBNP, and serum YKL-40." (PMID 31426765, 2019).
Stroke (continued). "The levels of pro-inflammatory cytokines (e.g., IL-6, IL-1β, and TNF-α) were all induced by stroke in control mice." (PMID 31771656, 2019). "In a clinical trial involving 158 healthy volunteers and 158 stroke patients, the levels of various inflammatory factors were elevated in patients with splenic contraction, with significant differences in IFN-γ, IL-6, IL-10, IL-12 and IL-13." (PMID 30700305, 2019). "Treatment with DS2 significantly decreased circulating IL-6 (0.1 mg/kg, P < 0.01; 1 and 4 mg/kg, P < 0.05), IL-17 and TNF-α levels (P < 0.05 and P < 0.001, respectively following treatment) at 3-days post-stroke." (PMID 31736685, 2019). "Similar to the effect of miR155, an antagomir for miR210 decreased expression of proinflammatory cytokines IL6, TNFα, IL1β, CCL2, and CCL3 reducing the neurological impairment, putting miR210 as potent regulator of inflammation during stroke recovery." (PMID 31543756, 2019). "For example, spleen cells collected from stroke model mice show a stronger ability to secrete inflammatory cytokines, including TNF-α, IL-6, monocyte chemoattractant protein-1 (MCP-1) and IFN-γ, than those collected from normal mice." (PMID 30700305, 2019). "Our data show that BDMPs increase the infiltration of leukocytes, microglia/macrophages and neutrophils, and the expression of immune factors IL1β, IL6, and TNF-α in the IBZ of stroke mice." (PMID 31993045, 2019). "The proinflammatory cytokine production of interleukin-1β (IL-1β), IL-6, and interferon-γ (IFN-γ) in the brain was upregulated in the vehicle-treated WT and AHRflx/flx mice at 48 h after stroke." (PMID 31606043, 2019). "They regulate expression of molecules important in stroke recovery including IL4, IL10, and BDNF in microglia and down-regulate iNOS and IL6." (PMID 31543756, 2019). "We found that EP4 receptor activation with L-902,688 potently reduces levels of some of the key mediators of stroke-induced BBB damage including IL-1β, IL-6, MMP-3, and MMP-9." (PMID 29527151, 2018). "Previous studies in animal models and in stroke patients have shown that continued production of cytokines such as IFNγ, TNFα, IL11, IL-1β, IL-1ra and IL-6 induces and maintains the M1 polarization state." (PMID 30584250, 2018). "These are partly verified by our findings revealing NF-κB activation and the expression of target genes, including TNF-α, IL-1β, IL-6, iNOS, and COX-2, in KO stroke mice." (PMID 30622459, 2018). "In summary, the major effects of MLC901 are the reduction of neutrophil recruitment, the reduction of microglia activation and the reduction of pro-inflammatory mediators (TNFα, IL6, IL1β, CCL2) production induced by stroke." (PMID 30584250, 2018). "The pro-inflammatory cytokine IL-6 and hs-CRP was reported to reflect the degree of brain ischemic damage and stroke." (PMID 30514242, 2018). "Stroke rats exhibited significantly higher gene expression and protein levels of TNF-α and IL-6 in brain and lung tissue homogenates compared to Sham animals." (PMID 30290827, 2018). "Thus, it is unclear whether the overall effect of IL-6 is beneficial or detrimental in the context of stroke, although in clinical studies, serum levels of IL-6 were suggested as a good predictor of in-hospital mortality in patients that had suffered an acute ischemic stroke." (PMID 28115020, 2017). "Several studies have shown that the percentages of cytotoxic T cells, natural killer (NK) cells, and B lymphocytes, and serum levels of TNF-α, IFN-γ, C-reactive protein (CRP), IL-4, IL-6, IL-10, and TGF-β are altered after stroke." (PMID 27682880, 2017). "Stroke induces rapid microglial activation and promotes the secretion of a variety of inflammatory mediators including IL-1β, TNF-α, and IL-6." (PMID 29202856, 2017). "Here, we showed that IFN-γ was negatively correlated with lesion volume on day 3 after stroke, but that CRP, IL-6, and IL-23 were positively correlated with lesion volume at that time point." (PMID 27682880, 2017).
Stroke (continued). "Previous studies showed it has a strong inhibitory effect of IL1β, IL6, IL10, TNF and other circulating cytokines, and suggested a potential therapeutic for stroke patients." (PMID 27672514, 2016). "Production of IL-1, IL-6, IL-10 and TNF-α as a consequence of cerebral insult from stroke can be sensed by the hypothalamus to activate the HPA axis for excessive glucocorticoid release." (PMID 26742037, 2016). "In this study, we determined that bone fracture 6 hours before stroke increased CD68+ macrophages, the levels of IL-1ß and IL-6 in the peri-infarct region, which was accompanied by increased neuronal death and behavior dysfunction." (PMID 27089041, 2016). "Pro-inflammatory mediators (such as IL-6, IL-1β, and TNF-α) contribute to expanding the area of brain injury in the context of stroke." (PMID 27549161, 2016). "Numerous cytokines and growth factors such as interleukin-1α (IL-1α), IL-6 and thromobospondin-1 (TSP-1) have also been shown to contribute to the process of angiongesis after stroke." (PMID 27275837, 2016). "The levels of both miR-9 and miR-124 were positively correlated with National Institutes of Health Stroke Scale (NIHSS) scores, infarct volumes and serum concentrations of IL-6." (PMID 27661079, 2016). "Researchers have demonstrated that the following brain insult cytokine levels are elevated as a result of increased production from inflammatory cells with IL-1, IL-6, and tumor necrosis factor-alpha (TNF-α) and being the most studied for stroke." (PMID 26074992, 2015). "Recently, the predictive ability of both, IL-6 and CRP within 3 days after stroke for post-stroke infection has been reported." (PMID 25613713, 2015). "More specifically, we studied the associations of adiponectin, leptin, and the interleukin-6 product CRP (used as a proxy for interleukin-6) with incident CHD and stroke in the Inter99 study." (PMID 26035431, 2015). "High levels of IL-6 and TNF-α predicted incident coronary heart disease, stroke, and congestive heart failure." (PMID 25722960, 2015). "During the third day following stroke onset, two well-known proteins of the inflammatory pathway—CRP and IL-6—were found to be indicators of prognosis in our population." (PMID 26543408, 2015). "At 24 hours post-stroke, IGF-1 treatment continued to inhibit selective pro-inflammatory markers, such as IL-6, the pleitrophic cytokine IL-13 and the chemoattractants CCL2 and GRO-KC." (PMID 24618563, 2014). "Interleukin-6 (IL-6) and tumor necrosis factor-alpha (TNF-α) are some of the most studied cytokines in stroke-related inflammation." (PMID 25086655, 2014). "Interestingly, IL-6 levels were markedly higher in ES than in pMCAO and LC, which may be a marker of a more aggressive surgical procedure in ES and may also explain the higher mortality and larger stroke sizes in this model." (PMID 25086655, 2014). "In subjects with stroke classified as LAAS and metabolic syndrome, PWV was more significantly and positively related to CRP, IL-1β, IL-6, TNF-α, vWF and PAI-1 compared to subjects without metabolic syndrome and the same subtype of stroke." (PMID 24571954, 2014). "Several inflammatory genes, like interleukin-6 (IL-6), tumor-necrosis factor-alpha (TNF-α) and matrix metalloproteinase-3 (MMP-3), were also found to confer risks for stroke." (PMID 23356535, 2013). "ADMA was positively correlated with IL-6 and CRP at 3 and 7 days and with TIMP-1 at 6 and 24 hours, 3 and 7 days after stroke onset." (PMID 23158556, 2012). "SDMA was positively correlated with MCP-1 at 6 hours and 3 and 7 days, with IL-6 at 3 and 7 days and with TIMP-1 at 7 days after stroke onset." (PMID 23158556, 2012). "We have also found significant relationships between a greater neuroserpin decrease within the first 24 hours from stroke onset and lower levels of the inflammatory biomarkers ICAM-1 and IL-6 at 24 hours." (PMID 21569344, 2011).